PSAP (prosaposin)
Diseases named in the same sentence as PSAP in open-access papers (continued):
Sharing a sentence is not in itself a finding about the gene and the disease.
schizophrenia (3 papers, 2018 to 2026). A major psychotic disorder characterized by abnormalities in the perception or expression of reality. "PSAP mutations are linked to Parkinson’s disease (PD), and an association of single nucleotide polymorphisms (SNPs) in the PSAP gene with schizophrenia was revealed in a Dutch population." (PMID 36233357, 2022). "Apart from the connections with neurodegenerative diseases, including PD, FTLD, and LBD, PSAP and PGRN are also genetically linked to schizophrenia." (PMID 36233357, 2022). "In conclusion, PSAP and PGRN downregulation in the cingulate cortex is associated with schizophrenia pathophysiology." (PMID 36233357, 2022). "Genetic associations of PSAP and PGRN with schizophrenia have been reported." (PMID 36233357, 2022). "Interestingly, SNPs in PSAP and PGRN were found to be associated with schizophrenia." (PMID 36233357, 2022). "In conclusion, our study extends to previous human genetic findings, and adds neuropathological and in vivo animal data, suggesting an important role of PSAP and PGRN in schizophrenia pathophysiology." (PMID 36233357, 2022). "We found that PSAP and PGRN levels are reduced specifically in schizophrenia patients." (PMID 36233357, 2022). "Therefore, the involvement of PSAP and PGRN in schizophrenia pathogenesis is possible." (PMID 36233357, 2022). "Therefore, future mechanistic studies on the role of PSAP and PGRN in schizophrenia could bring novel insights into the pathogenesis of schizophrenia, with implications for drug development." (PMID 36233357, 2022). "Since we found decreases in both proteins in the cingulate cortex of schizophrenia patients, and PSAP changes seemed more specific than PGRN, we wondered whether PSAP deletion in the cingulate cortex of mice will influence the levels of PGRN and mouse behavior." (PMID 36233357, 2022). "Since PSAP and PGRN are emerging targets for therapeutic development in FTLD, and therapies against negative symptoms are lacking in schizophrenia, it is highly relevant to study PSAP and PGRN levels in schizophrenia." (PMID 36233357, 2022). "The PSAP or PGRN levels are not influenced by neuroleptic treatment; their decreases are related to schizophrenia pathogenesis." (PMID 36233357, 2022).
sphingolipidoses (3 papers, 2017 to 2025). "Prosaposin mutations cause some of the severest forms of sphingolipidoses, and are associated with perinatal lethality in mice, hampering studies on disease progression." (PMID 28389479, 2017).
breast tumor (2 papers, 2015 to 2023). "Transcript levels of HOXC11 and PSAP mRNA were found to correlate significantly in primary breast tumour tissue (rS = 0.7745, p <0.0001)." (PMID 26341737, 2015). "Transcript levels of HOXC11 and PSAP correlated strongly in samples of primary breast tumours (r = 0.7692, n = 51)." (PMID 26341737, 2015).
colorectal cancer (2 papers, 2025). A primary or metastatic malignant neoplasm that affects the colon or rectum. "Multiple SASP-linked proteins that rose in GCR-exposed mouse serum including, PSAP, THBS1, TIMP2, CST3, and PSMA6 are broadly detected in human malignancies, including breast and colorectal cancers were upregulated after GCR exposure." (PMID 41516087, 2025). "For instance, Prosaposin (PSAP), Endoplasmic reticulum resident protein 44 (ERP44), Proteasome subunit alpha type-6 (PSMA6), and Histone H4 (HIS1H4A) were highly expressed in most of the breast and colorectal cancer samples." (PMID 41516087, 2025).
COVID-19 (2 papers, 2022 to 2024). A disease caused by infection with severe acute respiratory syndrome coronavirus 2. "We also found a strong association between HRCT score and PSAP, a gene involved in antigen presentation and male fertility, both are perturbed in severe COVID-19 patients." (PMID 36532041, 2022). "Finally, using a Bayesian Network model, we identified FOS, CXCL8, IL1β, CST3, PSAP, CD45 and CD74 as predictors of the COVID-19 disease." (PMID 36532041, 2022). "Importantly, above immune findings were used for a Bayesian network model, which significantly revealed FOS, CXCL8, IL1β, CST3, PSAP, CD45 and CD74 as COVID-19 severity predictors." (PMID 36532041, 2022).
Fabry disease (2 papers, 2009 to 2025). Fabry disease (FD) is a progressive, inherited, multisystemic lysosomal storage disease characterized by specific neurological, cutaneous, renal, cardiovascular, cochleo-vestibular and cerebrovascular manifestations. "Lipid marked with footnotes c and e indicate that there was a statistically significant elevation when compared to the appropriate control group (infantile/late infantile controls for pSap-d, SapB-d, and MLD; adult controls for Fabry disease)." (PMID 19267410, 2009). "In this study, an elevated level of Globotriaosylsphingosine (Lyso-Gb3), an already known biomarker for Fabry disease, was confirmed in the knock-out cells of the GLA, GNPTAB, and PSAP genes and models for Fabry, mucolipidosis II/III (ML II/III), and combined saposin deficiency, respectively." (PMID 40650054, 2025).
fibrosarcoma (2 papers, 2025). A malignant mesenchymal fibroblastic neoplasm affecting the soft tissue and bone. "The findings indicate that TFPI-2 reduces the invasive and migratory capabilities of tumor cells by interacting with PSAP, offering a novel viewpoint and potential target for fibrosarcoma treatment." (PMID 40801564, 2025). "In fibrosarcoma, PSAP-TFPI-2 interaction suppresses tumor progression." (PMID 40801564, 2025). "PSAP’s interaction with TFPI-2 also presents a vulnerability in fibrosarcoma." (PMID 40801564, 2025).
Infertility (2 papers, 2018 to 2022). "It is well-known that 40–50% of infertility is due to the “male factor” and proteins such as PSAP or others identified will be interesting to explore in future studies of human infertility." (PMID 29929489, 2018).
leukodystrophy (2 papers, 2018 to 2022). Leukodystrophies are a group of rare, progressive, metabolic, genetic diseases that affect the brain, spinal cord and often the peripheral nerves. "P52 carried a heterozygous likely pathogenic variant in the PSAP gene which was previously associated with leukodystrophy in the autosomal recessive form." (PMID 35752680, 2022).
lung adenocarcinoma (2 papers, 2017 to 2022). A carcinoma that arises from the lung and is characterized by the presence of malignant glandular epithelial cells. "The expression of PSAP in lung adenocarcinoma was higher than that in normal tissues, but further exploration the expression level and prognostic significance of PSAP was needed in LUSC." (PMID 36311764, 2022). "To evaluate the possibility for clinical application, we tested the expression of DNAJB1, MCU, MPRIP, PSAP, RAI14, ZNF131 and TMC5 in 71 lung adenocarcinoma samples and paired adjacent normal tissue samples (>2 cm away from the tumor) from patients who underwent lobectomy or pneumonectomy." (PMID 29285248, 2017).
lung carcinoma (2 papers, 2022 to 2024). "The levels of PSAP and SULF-1 were measured in PE of MPM and control (lung cancer and benign pleural disease) patients by enzyme-linked immunosorbent assay (ELISA)." (PMID 36359323, 2022). "Pleural effusions from a total of 44 patients (23 with mesothelioma, 8 with lung cancer, and 13 with non-malignant disease) were analyzed for prosaposin and SULF-1 by enzyme-linked immunosorbent assay." (PMID 36359323, 2022). "Recently, PSAP was shown to promote GBM invasion and epithelial–mesenchymal transition (EMT)-like processes via the TGF-β1/Smad signaling pathway, a strategy used by lung cancer cells to acquire radioresistance." (PMID 38212481, 2024).
melanoma (2 papers, 2014 to 2026). A malignant, usually aggressive tumor composed of atypical, neoplastic melanocytes. "Among these, PSAP emerged as the most robustly and consistently modulated effector, upregulated in primary melanoma cells and downregulated in metastatic ones upon sIL-15Rα stimulation." (PMID 42064067, 2026). "Altogether, these findings identify PSAP as a stage-specific mediator of tmbIL-15 reverse signaling in melanoma, integrating immune and EMT-related cues with potential implications for tumor progression and microenvironmental remodeling." (PMID 42064067, 2026). "However, PSAP, MYO1B and BUB3 seem to follow the same trend as shown by proteomics analysis in all three melanoma cell lines." (PMID 24743044, 2014).
metastatic carcinoma (2 papers, 2010 to 2024). A carcinoma which has spread from the original site of growth to another anatomic site. "Therefore, it is conceivable that PSAP overexpression may greatly contributes to Cer-level reduction in invasive and metastatic cancer cells." (PMID 20132547, 2010).
pancreatic ductal adenocarcinoma (2 papers, 2010 to 2022). An infiltrating adenocarcinoma that arises from the epithelial cells of the pancreas. "Very recently, a glycoproteomic study has identified PSAP among other glycoproteins secreted by pancreatic ductal adenocarcinoma (PDAC) cell lines." (PMID 36359323, 2022).
Polydipsia (2 papers, 2018 to 2026). Excessive thirst manifested by excessive fluid intake. "We found that PSAP is highly expressed in the subfornical organ (SFO), a thirst center, in SAP-D-deficient (SAP-D−/−) mice, which develop primary polydipsia." (PMID 41438692, 2026). "The infiltration of PSAP/PGRN-expressing microglia alongside polydipsia onset suggests that these proteins may play a prominent role in the disease's progression." (PMID 41438692, 2026). "In summary, we found that in SAP-D-deficient mice, the infiltration of microglia/macrophage strongly enriched with PSAP and PGRN increased in parallel with the progression of polydipsia and with the expression of c-Fos, which is deeply associated with drinking behavior." (PMID 41438692, 2026). "Notably, this is the first report linking PSAP to polydipsia." (PMID 41438692, 2026). "In this study, we identified activated microglia/macrophages with high PSAP and PGRN expression infiltrating the SFO in SAP-D−/− mice as polydipsia progressed." (PMID 41438692, 2026). "GPR37 gene expression around the SFO was significantly higher in SAP-D−/− mice than in WT mice, suggesting that PSAP secretion from microglia activates ERK via GPR37, inducing c-Fos expression and excessive water intake, ultimately driving polydipsia onset and progression." (PMID 41438692, 2026). "In this study, we investigated PSAP and PGRN expression at the cell and intracellular level, around the SFO in SAP-D−/− mice, and the involvement of those proteins in the development of polydipsia in SAP-D−/−, with respect to c-Fos expression in that area." (PMID 41438692, 2026).
Sepsis (2 papers, 2018 to 2024). Sepsis is defined as life-threatening organ dysfunction caused by a dysregulated host response to infection. "Cathepsin B (CatB), vascular cell adhesion protein 1 (VCAM-1), neutrophil gelatinase-associated lipocalin (NGAL), protein S100-A9, prosaposin, and thrombospondin-1 levels were significantly increased in the patients with sepsis compared with those of the controls (p < 0.001)." (PMID 39049003, 2024). "Finally, we selected six DEPs that were closely associated with sepsis: cathepsin B (CatB), vascular endothelial cell adhesion molecule (VCAM-1), neutrophil gelatinase-associated lipoprotein (NGAL), protein S100-A9, prosaposin, and thrombospondin-1 (TSP-1)." (PMID 39049003, 2024). "This may be correlated with renal injury in sepsis patients, as the kidney is known to be a major secretor of prosaposin." (PMID 30279625, 2018). "CatB, VCAM-1, NGAL, S100-A9, prosaposin, and TSP-1 levels were significantly increased in the sepsis group (p < 0.001) compared with those of the controls." (PMID 39049003, 2024).
atopic dermatitis (1 paper, 2022). "The level of prosaposin in atopic dermatitis skin was decreased by 30%, in comparison to that of controls, indicating that this impairment is possibly associated with irregular SC formation in atopic skin via lower stimulation of sphingomyelinase or beta-glucocerebrosidase." (PMID 35055292, 2022).
autism (1 paper, 2022). Persistent deficits in social interaction and communication and interaction as well as a markedly restricted repertoire of activity and interest as well as repetitive patterns of behavior. "PSAP is an important factor related to PGRN, further supporting that the PGRN-PSAP interaction is likely relevant to the molecular mechanisms underlying autism." (PMID 35318322, 2022). "To further clarify the mechanism by which PGRN is expressed at low levels in the VPA-induced rat model of autism, we assessed the expression of sortilin, PSAP and M6PR." (PMID 35318322, 2022). "Meanwhile, we found that PGRN might be regulated by the prosaposin (PSAP) pathway in the rat autism model." (PMID 35318322, 2022).
Batten disease (1 paper, 2025). "A recent paper exploring the proteomic changes in microglia with another LSD, Batten disease caused by loss of CLN3, identify similar changes to those seen here, including increased TTYH3, PTTG1IP, LAMTOR3, PSAP, STARD3NL, TSPAN7, TMEM192 and NPC1." (PMID 40608809, 2025).
brain ischemia (1 paper, 2019). Diminished or absent blood supply to the brain caused by obstruction (thrombosis or embolism) of an artery resulting in neurologic damage. "Recent studies have suggested that alternative splicing of pre-mRNAs encoding amyloid precursor protein, Bcl-x, extra domain A of fibronectin and prosaposin are implicated in rodent brain in fluid percussion, brain ischemia and facial nerve injury." (PMID 30846870, 2019).
C. perfringens infection (1 paper, 2021). "Following C. perfringens infection, some genes in the host intestinal mucosa were differentially down-regulated, for example, Coronin-1C, Receptor Protein-Tyrosine Phosphatases (RPTPs), and Prosaposin." (PMID 34959561, 2021).
cognitive decline (1 paper, 2025). "The study utilized longitudinal samples from the same individuals, and PSAP expression was found that PSAP expression was increased in samples collected after progression from MCI to mild AD (i.e., post-cognitive decline) compared to their pre-decline baseline." (PMID 40801564, 2025).
Cognitive impairment (1 paper, 2023). Abnormal cognition is characterized by deficits in thinking, reasoning, or remembering. "As a disease control study, we measured CSF PSAP levels in normal pressure hydrocephalus (NPH) patients, which is characterized by cognitive impairment." (PMID 37726325, 2023).
colon cancer (1 paper, 2025). "In contrast, hypoxia might also stimulate autophagy in colon cancer cells through the modulation of the translation of the highly conserved lysosomal glycoproteins PSAP and LAMP2, which in turn increase mitophagy and thus protect tumor cells." (PMID 39762799, 2025).
cortical dysplasia (1 paper, 2017). "And FSCN1, CRMP1, NDRG1, DPYSL5, MAP4, and FABP3 were selected for validation and identified to be increased in childhood cortical dysplasia patients, while PRDX6 and PSAP were identified decreased." (PMID 28222113, 2017).
deficiencies (1 paper, 2019). "PSAP deficiency has been shown in three rare genetic cases to result in a large amount of neuronal loss due to lysosomal deficiencies." (PMID 30862089, 2019).
Ductal adenocarcinomas (1 paper, 2025). "Ductal adenocarcinomas of the prostate may lose expression of typical prostate markers such as PSA, PSAP, and NKX3.1, particularly in advanced or metastatic stages." (PMID 40662033, 2025).
grand-mal epilepsy (1 paper, 2017). "Infants with PSAP deficiency presented multifocal myoclonus and cyanotic hypoxemia immediately after birth, grand-mal epilepsy in the following days, and cortical and white matter morphogenetic disorders." (PMID 28222113, 2017).
Hepatic steatosis (1 paper, 2025). Steatosis is a term used to denote lipid accumulation within hepatocytes. "CYN promotes hepatic steatosis by elevating proteins involved in lipid metabolism (acetyl-CoA carboxylase, stearoyl-CoA desaturase-1, prosaposin, and ACAA2 (3-ketoacyl-CoA thiolase mitochondrial)) and potentially impairing autophagy." (PMID 41227594, 2025).
hyperlipidemia (1 paper, 2022). "For example, we identified two heterozygous missense variants in PSAP in a 1-year-old patient with abdominal distention, hepatomegaly, and hyperlipidemia, and normal biomarker lyso-Gb1." (PMID 35614200, 2022).
Hypertension (1 paper, 2019). The presence of chronic increased pressure in the systemic arterial system. "Moreover, we had a number of suggestive genes arise from our vascular tissue data, highlighted as having specific effects on the ECM including TIMP2, PSAP, FN1, VCAN, and LOX, each of which have been previously implicated in hypertension." (PMID 30931314, 2019).
Insulin resistance (1 paper, 2025). Increased resistance towards insulin, that is, diminished effectiveness of insulin in reducing blood glucose levels. "Therefore, we conducted this cross-sectional study to assess the levels of the peptides PSAP and EPDR1 in the blood of individuals with T2DM, as well as investigate any potential associations between these peptide levels and markers of insulin resistance among the subjects." (PMID 40642507, 2025). "Taken together, blood levels of EPDR1 and PSAP were considerably greater in T2DM patients compared to healthy controls and were correlated with enhanced insulin resistance levels." (PMID 40642507, 2025). "Therefore, increased serum PSAP and EPDR1 levels in T2DM participants suggest increased blood insulin resistance levels." (PMID 40642507, 2025). "Similar to this, increased PSAP and EPDR1 levels in the serum may be predicted by higher degrees of insulin resistance." (PMID 40642507, 2025). "The levels of PSAP and EPDR1 may be used as possible biomarkers to predict the emergence of insulin resistance and T2DM." (PMID 40642507, 2025).
ischemia (1 paper, 2018). A hypoperfusion of the BLOOD through an organ or tissue caused by a PATHOLOGIC CONSTRICTION or obstruction of its BLOOD VESSELS, or an absence of BLOOD CIRCULATION. "The lack of a difference in glutamate transporter current with GPR37L1 knocked out could reflect GPR37L1 not being activated under physiological conditions, since it is known that the expression and release of prosaposin are up‐regulated following ischemia." (PMID 28795439, 2018). "However, prosaposin expression and release are increased in ischemia and we found that expression of Gpr37l1 is increased in the penumbra of lesions caused by MCAO, so it is likely that glutamate transport activity is inhibited in these conditions." (PMID 28795439, 2018). "This could provide a neuroprotective mechanism when both glutamate and prosaposin are released during ischemia." (PMID 28795439, 2018).
lung fibrosis (1 paper, 2024). "In comparison to the neutrophilic cases, the IPA analysis of the proteomic datasets derived from horses with metachromatic inflammation revealed enrichment in pathways related to hypersensitivity reaction (CD44, ICAM1, SOD1, PSAP, CDH1) and lung fibrosis (AGER, TGFBR2, FBLN1, S100A9)." (PMID 39594673, 2024).
membranoproliferative glomerulonephritis (1 paper, 2012). Inflammation of the glomeruli characterized by deposits at the intraglomerular mesangium, resulting in thickening of the glomerular basement membrane, activation of complement, and impaired kidney function secondary to damaged glomeruli. "On the other hand, complement factor H (Ctf) and prosaposin (Psap) are relatively downregulated in ROP-Os/+ kidneys, similar to observations in membranoproliferative glomerulonephritis (MPGN) and tubular damage." (PMID 22813067, 2012).